FGFR3 (fibroblast growth factor receptor 3)
Diseases named in the same sentence as FGFR3 in open-access papers (continued):
Sharing a sentence is not in itself a finding about the gene and the disease.
rectal cancer (3 papers, 2022 to 2025). A primary or metastatic malignant neoplasm that affects the rectum. "The intersection of the candidate target genes in the MAPK pathway and the overexpressed genes in colon and rectal cancer in TCGA and GTEx was taken, and 5 candidate genes EFNA2, RPS6KA2, MAPK13, EFNA3 and FGFR3 were identified." (PMID 34998382, 2022). "A similar pattern was detectable in rectal cancer, where PIK3CA and PTEN alterations were significantly overrepresented in the RAS/BRAF‐altered subgroup and EGFR, ERBB2, FGFR1, and FGFR3 alterations were significantly overrepresented in the RAS/BRAF‐wt subgroup." (PMID 39865537, 2025).
seminoma (3 papers, 2014 to 2021). A radiosensitive malignant germ cell tumor found in the testis (especially undescended), and extragonadal sites (anterior mediastinum and pineal gland). "In filamin A-deficient TCam-2 seminoma cells, enhanced transcript levels of the pluripotency factors OCT3/4, NANOG and FGFR3 compared to filamin A-proficient cells have been found, indicating that filamin A is involved in determining stemness in seminomas." (PMID 34771736, 2021). "qPCR measurements revealed that FLNA-deficient cells show enhanced transcript levels of the stem cell markers OCT3/4, NANOG and FGFR3 in comparison to TCam-2 WT seminoma cells." (PMID 33266100, 2020).
sensory neuropathies (3 papers, 2021 to 2025). "This study facilitates future studies on the diagnostic relevance of anti-FGFR3 autoantibodies in sensory neuropathies." (PMID 41142778, 2025). "Although anti-FGFR3 antibodies have been recognized for a decade, their specificity, pathogenic role, and impact on treatment decisions in sensory neuropathies remain inconclusive." (PMID 41142778, 2025). "However, the initial study that associated FGFR3 antibodies with sensory neuropathy reported frequent trigeminal nerve involvement." (PMID 33588772, 2021). "Our findings address the critical need for standardizing anti-FGFR3 testing in sensory neuropathies." (PMID 41142778, 2025). "The intracellular domain of FGFR3 was found to be a target of IgG antibodies in a subgroup of patients with sensory neuropathy, particularly in idiopathic or autoimmune-related cases." (PMID 33588772, 2021). "Here, we provide a standardized and validated protocol for anti-FGFR3 antibody detection, and offer a method for antibody confirmation, thus paving the way for more accurate testing and multicenter investigations to understand the clinical relevance of anti-FGFR3 antibodies in sensory neuropathies." (PMID 41142778, 2025). "Recent studies have identified autoantibodies against fibroblast growth factor receptor 3 (FGFR3) as a potential biomarker for sensory neuropathies particularly affecting the dorsal root ganglia (DRG), such as sensory neuronopathy (SNN) and small fiber neuropathy (SFN)." (PMID 41142778, 2025). "However, the scope of these studies was restricted to measuring antibody titers in patients with pure sensory neuropathies or small fiber peripheral neuropathies, which excluded testing FGFR3 antibodies in patients with sensorimotor or motor neuropathies." (PMID 33588772, 2021). "In a multicenter prospective study, 15% of patients with a sensory neuropathy had FGFR3 antibodies; 2/3 of patients fulfilled the criteria for sensory neuronopathy, 17% for small-fiber neuropathy and 19% for other sensory neuropathies, the majority (89%) being non-length-dependent phenotypes." (PMID 39555481, 2024).
Turner syndrome (3 papers, 2017 to 2024). Turner syndrome is a chromosomal disorder associated with the complete or partial absence of an X chromosome. "We also found evidence that the absence of two X chromosomes leads to overexpression of genes associated with Turner syndrome, including Fgfr3 and Wnt4." (PMID 28818098, 2017). "Included in this group are four genes commonly associated with Turner syndrome (WNT4, MTHFR, FGFR3, and MEN1)." (PMID 28818098, 2017).
amyloid (2 papers, 2021 to 2024). "Taken together, our findings suggest that the FGF2 secretion induced by amyloid pathology is sufficient to promote FGFR3-mediated tau uptake in neurons." (PMID 38951140, 2024). "Unlike changes in FGF2, FGFR3 levels were not altered by Aβ treatment or amyloid pathology." (PMID 38951140, 2024).
astrocytoma (2 papers, 2023 to 2024). "HCMV major IE1 can interact with FGFR3 in astrocytoma cell lines, but the absence of FGFR3 leads to abnormal column cell development." (PMID 39205316, 2024).
autoimmune disease (2 papers, 2024 to 2025). A disorder resulting from loss of function or tissue destruction of an organ or multiple organs, arising from humoral or cellular immune responses of the individual to their own tissue constituents. "Immune‐mediated sensory neuronopathies (SNN) can occur alongside autoimmune disorders (e.g., Sjögren syndrome), involve autoantibodies (such as anti‐FGFR3 or anti‐AGO antibodies), or present in isolation." (PMID 40037793, 2025). "Criteria for inclusion included: (a) presence of anti‐AGO or FGFR3 antibodies, (b) coexistent autoimmune disorders (particularly Sjögren syndrome), or (c) clinical presentation indicative of an immune‐driven process." (PMID 40037793, 2025). "Among the participants, 18 patients were previously tested positive for anti‐AGO antibodies, 48 for anti‐FGFR3 antibodies, and 14 had an associated autoimmune disease without detectable anti‐AGO or FGFR3 antibodies." (PMID 40037793, 2025). "Eighteen patients had anti‐AGO antibodies, 48 had anti‐FGFR3 antibodies, and 14 had an autoimmune disease without detectable anti‐AGO or FGFR3 antibodies." (PMID 40037793, 2025).
benign prostatic hyperplasia (2 papers, 2005 to 2017). A non-cancerous nodular enlargement of the prostate gland. "FGFR3 immunoreactivity in benign prostatic hyperplasia (BPH) and CaP (n=26 and 57, respectively) had similar intensity and pattern." (PMID 15655558, 2005).
bone tumors (2 papers, 2023 to 2025). "This study identified a new class of skeletal stem cells in the endosteal space of bone marrow, which are abundant in young bone marrow, express Fgfr3 with osteoblast-chondrocyte transitional identities and can turn into bone tumor-making cells." (PMID 37185464, 2023).
cervical tumor (2 papers, 2005 to 2013). "To better characterize FGFR3 mutated cervical tumors and to find explanations for the apparent discrepancy in mutation rates, we looked for clinical and pathological features that may be specifically associated with FGFR3 mutation." (PMID 15869706, 2005). "FGFR3 expression was reduced in almost 60% of cervix tumors and when it was increased, it was in tumors of good prognosis." (PMID 23902722, 2013). "To further analyze the role of FGFR3 in cervical tumor progression, we extended our study to screen a total of 75 invasive tumors and 80 cervical intraepithelial neoplasias (40 low-grade and 40 high-grade lesions)." (PMID 15869706, 2005). "Age and association with minor HPV types may thus not be independent characteristics of patients with FGFR3 mutated cervical tumor." (PMID 15869706, 2005).
chondrosarcoma (2 papers, 2013 to 2020). A malignant cartilaginous matrix-producing mesenchymal neoplasm arising from the bone and soft tissue. "As RCS cells express high levels of wild-type FGFR3, we used human chondrosarcoma (HCS-2/8) cells to observe unequivocal effects of the transduced FGFR3 mutants." (PMID 24324705, 2013). "As rat chondrosarcoma (RCS) chondrocytic cells express high levels of FGFR3, exogenous administration of FGF2 readily recapitulates cellular processes occurring in FGFR3-related skeletal dysplasias." (PMID 24324705, 2013).
Cirrhosis (2 papers, 2022 to 2024). A chronic disorder of the liver in which liver tissue becomes scarred and is partially replaced by regenerative nodules and fibrotic tissue resulting in loss of liver function. "Moreover, the expression of both FGFR3 and FGFR4 was significantly associated with cirrhosis (p < 0.05) while FGFR4 was also upregulated in HCV-positive HCC patients (p < 0.002)." (PMID 35683481, 2022). "Thus, we can speculate that the loss of FGFR3 may be involved in the development of cirrhosis rather than in neoplastic transformation in our cases." (PMID 38254797, 2024). "The clinicopathological analyses were performed for FGFR1, FGFR2, FGFR3 and FGFR4 against age, sex, grade stages, tumor stages, HCV, AFP, cirrhosis, vascular invasion, and cell type (atypical, dysplastic/polygonal, neoplastic) using different statistical approaches." (PMID 35683481, 2022). "Moreover, FGFR3 and FGFR4 showed a significant upregulation in advanced stages of HCC patients.The results from three independent cohorts suggested a strong positive correlation between FGFR2 expression and HCV-positive cirrhosis patients as well as HCV-positive HCC patients." (PMID 35683481, 2022).
cleft palate (2 papers, 2015 to 2019). Cleft palate is a fissure type embryopathy that affects the soft and hard palate to varying degrees. "Previous genetic screening demonstrates that the mutations of Fgfr1 and Fgfr3 are also associated with human cleft palate." (PMID 26332583, 2015).
cutaneous squamous cell carcinoma (2 papers, 2016 to 2024). "Concomitant alterations in the MAP2K1 and FGFR3 genes, as it is in the present case, have been described in cases of cutaneous squamous cell carcinoma that presented a significant response to EGFR inhibitors (cetuximab)." (PMID 39273494, 2024).
dermopathy (2 papers, 2019 to 2021). "A hypothesis for absence of skin changes in CS‐39 could be the presence of an additional sequence variant that could cause dysregulation downstream of FGFR3 signaling." (PMID 31016899, 2019).
diabetic foot ulcer (2 papers, 2023 to 2025). "Fig7B and 7C displays the expression levels of CCL20, CXCL13, FGFR2, FGFR3, PI3, PLA2G2A, and S100A8 across the six cell types.The results showed that the key pathogenic genes of diabetic foot ulcer were mainly involved in keratinocytes and neutrophils." (PMID 40749079, 2025). "Specifically, monocytes/macrophages increased expression of several apoptosis genes (including BCL2, FGFR3, FGFR1, CTH, CASP3, IL19, NME5, and S100A8/9) in diabetic foot ulcers compared to monocytes/macrophages in non-diabetic wounds." (PMID 38127424, 2023).
epidermal nevus (2 papers, 2011 to 2014). "Germline mutations in the FGFR3 gene have found to be the etiology of epidermal nevus." (PMID 25206237, 2014).
esophageal cancer (2 papers, 2020 to 2023). A primary or metastatic malignant neoplasm involving the esophagus. "In previous studies of esophageal cancer, FGFR3 was associated with tumor proliferation." (PMID 33381388, 2020).
ganglioglioma (2 papers, 2024 to 2025). A well differentiated, slow growing neuroepithelial neoplasm composed of neoplastic, mature ganglion cells and neoplastic glial cells. "Although ganglioglioma may harbor mutations or fusions of FGFR genes, FGFR3::TACC3 fusion has not been observed in any tumor with histological features of ganglioglioma." (PMID 38730596, 2024).
growth disorders (2 papers, 2016 to 2025). "In DGD patients, growth disorders, especially defective matrix functions such as genetic alterations in genes (e.g., COL 1 A, COLA2), or alterations in receptor formation (FGFR3) contribute to bone fragility and low density which can precipitate pathological fracture." (PMID 41286975, 2025).
hemangioblastoma (2 papers, 2022 to 2025). "One study examined a cohort of 20 VHL patients using laser-scanning cytometry and revealed elevated FGFR2 and FGFR3 expression in hemangioblastomas compared with clear-cell renal-cell carcinomas." (PMID 40393028, 2025). "Our analysis revealed FGFR2 expression in most of the hemangioblastoma samples, while FGFR3 were mostly negative." (PMID 40393028, 2025). "Notably, while RCC tissues demonstrated higher levels of phosphorylated VEGFR-2 when compared to hemangioblastomas, the protein levels of fibroblast growth factor receptor 3 (FGFR3) and FGFR ligand (FGFR substrate 2) were higher in hemangioblastomas relative to RCC." (PMID 36358730, 2022).
Hydrocephalus (2 papers, 2021 to 2024). Hydrocephalus is an active distension of the ventricular system of the brain resulting from inadequate passage of CSF from its point of production within the cerebral ventricles to its point of absorption into the systemic circulation. "Similarly, a girl carrying c.1133G > A and c.1138G > A in FGFR3 showed more severe clinical and radiological characteristics than classic ACH patients, with respiratory distress, pulmonary hypoplasia, hydrocephalus and cervicomedullary compression." (PMID 38281003, 2024).
inverted urothelial papilloma (2 papers, 2023 to 2025). An endophytic lesion in the urinary tract which shares several morphologic features with urothelial papilloma.
Lewy body dementia (2 papers, 2022 to 2024). A progressive form of dementia characterized by the presence of protein deposits called Lewy bodies in the midbrain and cerebral cortex, and loss of cholinergic and dopaminergic neurons. "Increased FGFR3 staining has been documented in the anterior cingulate cortex of patients with Lewy Body dementia (LBD)." (PMID 38638441, 2024).
lumbar spinal stenosis (2 papers, 2024 to 2025). A spinal stenosis that involves the lumbar region of vertebral column. "Another gene that is implicated in lumbar spinal stenosis is the fibroblast growth factor receptor 3 (FGFR3), a gene heavily implicated in bone elongation." (PMID 40083985, 2025).
mesothelioma (2 papers, 2020 to 2021). A usually malignant and aggressive neoplasm of the mesothelium which is often associated with exposure to asbestos. "Mesothelioma (MESO) and DLBC had a relatively high proportion of shallow deletion and were also the tumor type with relatively lower FGFR3 expression." (PMID 34160364, 2021).
metastatic colorectal cancer (2 papers, 2017 to 2018). "The preliminary response data from that early trial together with our findings on prevalence and prognostic impact make FGFR3 overexpression a potential therapeutic target also in metastatic colorectal cancer." (PMID 30181810, 2018). "At the pathway level, we detected that the alteration rate (mutation and copy number variation) of the genes involved in MAPK signaling pathways, including FGFR1, FGFR2, FGFR3, FGFR4, BRAF, and MEK, was significantly lower in metastatic colorectal cancer tissue compared to the primary site." (PMID 29038591, 2017).
myeloid malignancies (2 papers, 2021). "Yet, of the remaining genes, FGFR3 was involved in proliferation and SETBP1 somatic mutations have been connected with myeloid malignancies." (PMID 34906245, 2021).
myopia (2 papers, 2024 to 2025). "The FGFR3 gene encodes fibroblast growth factor receptor 3, mainly expressed in cartilage and lens, and mutations in FGFR3 gene can also lead to clinical manifestations of myopia." (PMID 38790056, 2024). "Analysis of protein interactions in the STRING online database revealed that the ARID1A protein interacts with the high myopia gene-related proteins FGFR3, ASXL1, ERBB3, and SOX4, whereas the ARID1A protein antagonizes the ARID1B protein." (PMID 38790056, 2024). "It was found that high myopic associated proteins (ASXL1 FGFR3 ERBB3 SOX4) can affect ARID1B protein by affecting ARIDIA protein, and COL2A1 protein can also affect ARIDIA protein by affecting FGFR3 protein, resulting in the clinical phenotype of patients with high myopia." (PMID 38790056, 2024). "Therefore, we predict that mutations in the ARID1B gene would result in decreased expression of wild-type protein, relatively enhanced activity of ARIDIA protein, low expression of FGFR3 protein, and low expression of COL2A1 protein leading to clinical phenotypes associated with myopia." (PMID 38790056, 2024).
osteoporosis (2 papers, 2023 to 2024). A condition of reduced bone mass, with decreased cortical thickness and a decrease in the number and size of the trabeculae of cancellous bone (but normal chemical composition), resulting in increased fracture incidence. "Through targeting FGFR3, MiR-99b-5p can exhibit inhibitory effects on osteoblast proliferation and differentiation, thereby affecting bone formation in osteoporosis progression." (PMID 39268461, 2024).
pancreatic adenocarcinoma (2 papers, 2013 to 2023). "This suggests that as in pancreatic adenocarcinoma cell lines with epithelial phenotype, FGFR3 limits beta cell growth." (PMID 23902722, 2013).
pancreatic ductal adenocarcinoma (2 papers, 2013 to 2020). An infiltrating adenocarcinoma that arises from the epithelial cells of the pancreas. "63% of the intraductal papillary mucinous neoplasms and 30% of the pancreatic ductal adenocarcinomas showed total loss of FGFR3 signal." (PMID 23902722, 2013). "Earlier studies established the oncogenic role of ZIC2 in pancreatic ductal adenocarcinoma cells by activating the expressions of FGFR3 and ANXA836." (PMID 32066655, 2020). "The most relevant finding of this study is the tumor suppressive properties of FGFR3 in pancreatic ductal adenocarcinoma epithelial cells." (PMID 23902722, 2013).
papillary bladder urothelial carcinoma (2 papers, 2016 to 2021). "For example, certain mutations, such as that of FGFR3, are found in approximately 75% of low‐grade papillary bladder urothelial carcinoma, while overexpression of the FGFR3 protein is associated with high‐grade, aggressive disease." (PMID 34114376, 2021). "Missense mutations of fibroblast growth factor receptor 3 (FGFR3) occur in up to 80% of low-grade papillary urothelial carcinoma of the bladder (LGP-UCB) suggesting that these mutations are tumor drivers, although direct experimental evidence is lacking." (PMID 27157475, 2016).
paraganglioma (2 papers, 2019 to 2021). A benign or malignant neoplasm arising from paraganglia located along the sympathetic or parasympathetic nerves. "On the contrary, almost no FGFR3 mutations were observed in ACC, CHOL, DLBC, KICH, pheochromocytoma and paraganglioma (PCPG), TGCT, THCA, THYM, and uveal Melanoma (UVM)." (PMID 34160364, 2021).
Parkinson disease (2 papers, 2014 to 2022). A progressive degenerative disorder of the central nervous system characterized by loss of dopamine producing neurons in the substantia nigra and the presence of Lewy bodies in the substantia nigra and locus coeruleus. "In our study, the gene clusters that were significantly associated with the expression levels of FGFR3, has-miR-486-5p, and lnc-KCNH5-1 also focused on Parkinson’s disease pathway." (PMID 35784838, 2022). "Additionally, in silico analyses of these signatures revealed that FGFR3, has-miR-486-5p, and lnc-KCNH5-1 and pathways associated with Cytokine-cytokine receptor interaction, Oxidative phosphorylation, and Parkinson’s disease may play a vital role in developing TLE+HS." (PMID 35784838, 2022).
Pfeiffer syndrome (2 papers, 2019 to 2023). Pfeiffer syndrome (PS) is a common form of acrocephalosyndactyly, a group of inherited congenital malformation disorders, characterized by variable degrees of bicoronal craniosynostosis, variable hand and foot malformations and various other associated manifestations. "The finding of the p.Ala391Glu variant in CS‐39 expands the phenotype associated with this specific variant and suggests further molecular heterogeneity with involvement of FGFR3 with Pfeiffer syndrome." (PMID 31016899, 2019). "Pfeiffer syndrome pathogenic variants have not been identified in FGFR3 (OMIM 134934)." (PMID 31016899, 2019).